AHR (aryl hydrocarbon receptor)
Diseases named in the same sentence as AHR in open-access papers (continued):
Sharing a sentence is not in itself a finding about the gene and the disease.
Stroke (continued). "Post-stroke treatment of aged WT mice with microbiota-derived indole-based ligands of AHR reduced both infarct volume and neurological deficits at 24 hours." (PMID 37790313, 2023). "We found that MG AHR expression is increased in human brain after stroke and after ex vivo oxygen-glucose deprivation and reperfusion (OGD/R)." (PMID 37790313, 2023). "Immunohistochemical analysis of brain samples from stroke patients showed significant increase in expression of AHR in Iba-1 + cells (MG and other myeloid cells) after stroke, compared to non-stroke age-matched controls." (PMID 37790313, 2023). "Recent studies have highlighted the crucial role of the gut microbiota and its metabolites in mediating post-stroke immune response through various molecular pathways, including the aryl hydrocarbon receptor (AHR) pathway." (PMID 37790313, 2023). "Our results do not exclude indirect beneficial effects of indole-derived ligands of AHR on post-stroke neuroinflammation." (PMID 37790313, 2023). "In conclusion, both host-derived and microbiota-derived ligands play a role after stroke by activating AHR in MG and other immune cells." (PMID 37790313, 2023). "We began by demonstrating the significant expression (known to be an indirect measure of activation) of AHR in MG and significant reduction of plasma levels of microbiota-derived indole-based ligands of AHR after human stroke." (PMID 37790313, 2023). "We performed immunohistochemical analysis of brain samples from stroke patients to assess MG AHR expression after stroke." (PMID 37790313, 2023). "Post-stroke treatment of GF mice with a cocktail of microbiota-derived indole-based ligands of AHR regulated MG-mediated neuroinflammation and molecules involved in antigen presentation (increased CD80, MHC-II, and CD11b)." (PMID 37790313, 2023). "Post-stroke administration of two different pharmacological antagonists of AHR reduced infarct volume at 48hrs." (PMID 37790313, 2023). "Post-stroke treatment of microbiota-dependent indole-based ligands of AHR regulated MG-mediated neuroinflammation and antigen presentation molecules in GF mice." (PMID 37790313, 2023). "In studies on AhR expression after traumatic brain injury or stroke, elevated expressions of AhR occur in the injured nervous system." (PMID 36232555, 2022). "Significant upregulation of AHR expression after stroke has been reported, which is shown to play a role in the cerebral ischemic injury." (PMID 36032153, 2022). "Taken together, this study identified the L-Kyn-AHR pathway as a novel mediator of brain injury during stroke, and validated TDO and AHR as new “druggable” targets for acute ischemia stroke." (PMID 36032153, 2022). "This discovery makes AhR even more attractive target for future therapies against stroke, which occurs mainly in older people." (PMID 34830207, 2021). "As such, Cuartero and colleagues recently found l-kynurenine to activate the AhR pathway in the brains of a mouse model of stroke and contribute to infarct volume in a Kyn-AhR dependent fashion." (PMID 34205235, 2021). "Although promising experimental evidence on the important role of AhR signaling pathway in stroke pathology was obtained, this topic is still unexplored and requires further research." (PMID 34830207, 2021). "In this Review, we will discuss currently available knowledge on the mechanisms of action of ERs, PPARs and AhR in experimental models of stroke and myocardial infarction and future perspectives to use them as novel targets in cardiovascular diseases." (PMID 34830207, 2021). "Recent data have shown that experimental stroke is followed by an increase in AhR/ARNT expression levels in neurons in vitro and in vivo." (PMID 32816128, 2020). "This study investigated the neuroprotective effects of AhR antagonist administration before reperfusion in a rat stroke model and influence of the timing of AhR antagonist administration on its neuroprotective effects." (PMID 32913241, 2020).
Stroke (continued). "The AhR also plays a role in acute ischemic brain injury (stroke) induced by middle cerebral artery occlusion, and is accompanied increased levels of kynurenine in the brain." (PMID 32932962, 2020). "In this study, we investigated the neuroprotective effects of AhR antagonism before reperfusion in a rat model of stroke induced by transient middle cerebral artery occlusion (tMCAO) and reperfusion." (PMID 32913241, 2020). "Further experiments and other cell type-specific deletion of AHR are needed in stroke settings to elucidate the AHR-dependent mechanisms." (PMID 31606043, 2019). "AHR-null mice and poststroke pharmacological inhibition of AHR with the competitive antagonist, 6,2′,4′-trimethoxyflavone (TMF), after stroke reduced ischemic infarct in association with neuroprotective and antiapoptotic effects." (PMID 31606043, 2019). "After stroke, the WT-vehicle brain lysates had significantly increased AHR activity compared with that in the normal WT brain lysates, which was reduced in the brain lysates of TMF-treated group." (PMID 31606043, 2019). "Our data are also in line with other authors who have demonstrated ischemia-induced increases in Fas, Caspase-3, BAX and AhR protein levels in in vitro and in vivo models of stroke." (PMID 30778709, 2019). "The AHR-mediated neurogenic effect was less likely to contribute to the enhanced working memory functions by 7 days after stroke compared to the anti-inflammatory effects." (PMID 31606043, 2019). "AHR activation points to damaging roles of acute ischemic inflammation and gliosis in stroke pathophysiology." (PMID 31606043, 2019). "KYN levels in the brain were also elevated in this model of stroke and, through activation of the AHR, played a deleterious role in cerebral ischemia." (PMID 27858116, 2017). "In this study, we demonstrated that patients with low stroke risk have increased mRNA expression of GATA-3, Foxp3, PU.1, AHR, IL-9, IL-22 and IL-10." (PMID 27115869, 2016). "TRP metabolism involves three pathways: kynurenine, 5-hydroxytryptamine, and indole, which potentially regulate post-stroke, may function as aryl hydrocarbon receptor agonists to modify neuronal excitotoxicity, and offer crucial targets for stroke treatment." (PMID 40556758, 2025). "Our findings suggest that one of the potential mechanisms leading to improved post-stroke recovery by AhR is achieved by improved hematoma resolution, suggesting that AhR-activated MG-mediated clearance of hematoma could be the mechanism of improved recovery." (PMID 40963261, 2025). "Furthermore, these indoles can inhibit microglial and NLRP3 inflammasome activation by engaging the microglial AHR, mitigating post-stroke neuroinflammation." (PMID 40723792, 2025). "A study showed that AhR expression is upregulated after stroke, and that postoperative treatment of aged stroke mice by using AhR ligands such as IPA and IAld resulted in significant reductions in infarct volume and neurological defects, as well as amelioration of MG-mediated neuroinflammation." (PMID 40556758, 2025). "Post-stroke treatment of microbiota-derived indole-based ligands of AHR is beneficial." (PMID 37790313, 2023). "We utilized metabolomics, flow cytometry, and microbiome sequencing techniques to determine whether post-stroke dysbiosis disrupts the supply of microbiota-derived ligands of AHR in humans." (PMID 37790313, 2023). "Previous studies have shown that the activation of Microglia and AHR by host-derived ligands, represented by kynurenine, is detrimental after stroke, while the effects of post-stroke modification in AHR microbiota-derived ligands, by indoles, remain poorly understood." (PMID 38257864, 2023). "Our results showed that MG AHR expression is increased after stroke in humans." (PMID 37790313, 2023).
Stroke (continued). "This clinical data gap is of high translational relevance in stroke immunology as multiple studies have reported that indole-based molecules have a significantly higher affinity, at physiological concentrations, for the human AHR compared to mouse AHR15,64." (PMID 37790313, 2023). "Thus, studying the effects of post-stroke dysbiosis on MG AHR activation is important for understanding the complex mechanisms underlying post-stroke inflammation and identifying new therapeutic targets for stroke." (PMID 37790313, 2023). "We hypothesize that restoring the balance between host-derived (kynurenine) and microbiota-derived (indoles) ligands of AHR is beneficial after stroke, offering a new potential avenue for therapeutic intervention in post-stroke neuroinflammation." (PMID 37790313, 2023). "While previous studies have shown that activation of MG AHR by host-derived ligands, such as kynurenine, is detrimental after stroke, the effects of post-stroke changes in microbiota-derived ligands of AHR, such as indoles, is unknown." (PMID 37790313, 2023). "Kyn-mediated activation of MG AHR is detrimental after stroke." (PMID 37790313, 2023). "AHR expression is increased in microglia (MG) from post-mortem brain samples of stroke patients." (PMID 37790313, 2023). "Our results demonstrate that restoring a balanced pool of host-derived and microbiota-derived molecules via post-stroke treatment with indole-based AHR ligands to compete with Kyn-based activation of AHR provides a net beneficial effect and improved post-stroke outcomes." (PMID 37790313, 2023). "Gut microbiota dysbiosis after stroke leads to abnormal tryptophan metabolism, and the decreased levels of AHR agonists may lead to enhanced neuroinflammation." (PMID 36032153, 2022). "Activated microglia and astrocyte play an important role in neuroinflammation after stroke, which may be achieved through the binding of the ligand to AHR." (PMID 36032153, 2022). "AHR is engaged in the regulation of acute ischemic brain injury and may be involved in chronic neuroinflammation after stroke." (PMID 36032153, 2022). "AHR can affect these responses by sensing microbiota metabolites especially tryptophan metabolites and is engaged in the regulation of acute ischemic brain injury and chronic neuroinflammation after stroke." (PMID 36032153, 2022). "There is an increasing body of evidence that blocking of AhR signaling pathway could be a promising strategy in stroke therapy." (PMID 34830207, 2021). "It has been shown that experimental stroke is followed by an increase of AhR in the murine brain." (PMID 34830207, 2021). "The AHR signaling pathway was significantly upregulated after stroke." (PMID 31606043, 2019). "In support of our hypothesis, it was shown in an experimental stroke model that interference of AhR with this pathway by complex formation with CREB and CBP could be responsible for the deleterious effects of AhR48." (PMID 26790370, 2016). "Thus, after stroke, crosstalk in the gut-brain axis may lead to gut microbiota dysbiosis and cause abnormal TRP metabolism, decreasing AhR agonists and inducing enhanced neuroinflammation through interactions with microglia and astrocytes." (PMID 40556758, 2025). "Additionally, the kynurenine (KYN)-AhR pathway has been identified as a crucial factor in mediating neuronal injury following experimental stroke, suggesting its potential as a therapeutic target for stroke treatment." (PMID 39767818, 2024). "Therefore, the attenuated inflammation by AHR inhibition may indirectly support neurogenesis after stroke." (PMID 31606043, 2019). "An additional novel line of research opened by our study is the possible implication of AhR, as a new potent druggable target, in disorders in which cognitive deficits are accompanied by hippocampal morphologic alterations, such as epilepsy, schizophrenia, or stroke." (PMID 30225360, 2018).
Stroke (continued). "Our results showed that post-stroke treatment of GF mice with a cocktail of IPA and IAld significantly increases expression of MG AHR, MHC-II, and CD80." (PMID 37790313, 2023). "Next, we tested the effects of post-stroke supplementation with microbiota-derived ligands of AHR in vivo using GF and aged WT MCAO models of stroke." (PMID 37790313, 2023). "The regulation of the AhR expression in the nervous system depends not only on internal stimuli, but also on external stimulation due to traumatic brain injury (TBI) or stroke." (PMID 36232555, 2022). "Because our study provided evidence that in rat brain undergoing perinatal asphyxia, DIM predominantly targets AhR and NMDA, we postulate that compounds that possess the ability to inhibit their signaling are promising therapeutic tools to prevent stroke." (PMID 32816128, 2020). "Because our study provided evidence that in rat brain undergoing perinatal asphyxia, DIM predominantly targets AhR and NMDA, we postulate that compounds that possess the ability to inhibit the signaling are promising therapeutic tools to prevent stroke." (PMID 32816128, 2020). "Recently, it has been shown that expression of aryl hydrocarbon receptor (AhR) and its heterodimerization partner ARNT was substantially increased in neuronal cells and the brain after experimental stroke in vitro and in vivo." (PMID 30778709, 2019). "In our stroke model, by contrast, nestin+ cell-specific AHRcKO mice and TMF treatment inhibited AHR and reduced acute ischemic inflammation." (PMID 31606043, 2019). "AHR is activated and overexpressed in neurons of peri-infarct, ischemic core, as well as the cortex regions in experimental MCAO mice, with a damaging role in stroke physiopathology, as revealed by the AhR agonist, which aggravated the stroke outcome." (PMID 39195495, 2024). "Most interestingly, the authors also demonstrated that inhibition of L-Kyn production by pharmacological blockade of TDO could decrease the activation of AHR signaling and reduce infarct volume in the MCAO stroke model." (PMID 36032153, 2022). "However, large datasets reporting alterations of both kyn-based and indole-based ligands AHR after human stroke are not currently available." (PMID 37790313, 2023). "Since AhR promotes apoptosis, controls ERα, and is highly expressed in brain tissue in experimental models of stroke, we hypothesize that anti-apoptotic action of DIM against OGD is mediated via inhibition of AhR/CYP1A1 and/or stimulation of ERα/CYP19A1 signaling pathways." (PMID 30778709, 2019).
skin inflammation (25 papers, 2019 to 2025). "We will also investigate the association of AhR-Trp metabolism and explore the functional significance of microbial Trp metabolites in skin inflammation." (PMID 35727505, 2022). "The clinical efficacy of tapinarof lends further support to the therapeutic targeting of the AHR pathway to harness its homeostatic and anti-inflammatory effect in skin inflammation." (PMID 40004095, 2025). "For instance, skin microbiota-derived indole-3-aldehyde has been shown to significantly reduce skin inflammation in AD by activating AhR, which in turn inhibits the expression of proinflammatory cytokines such as TSLP." (PMID 39770040, 2024). "AhR is highly expressed in innate lymphoid cells type 3 and Th17 cells, contributing to the skin inflammation mediated by the production of IL17 and IL22, whereas promotes the differentiation and function of regulatory T cells." (PMID 39770040, 2024). "AhR plays a significant role in AD pathogenesis through its interaction with particulate matter (PM), which exacerbates skin inflammation and barrier dysfunction." (PMID 39770040, 2024). "Several studies have identified various natural compounds that can modulate AhR activity, which is crucial for managing skin inflammation and maintaining skin barrier function." (PMID 39770040, 2024). "Our investigation reveals the collaborative involvement of the MAPK/NF-κB and AhR pathways in DNCB-induced AD-like skin inflammation and barrier dysfunction orchestrated by TSLP and periostin, effects substantially mitigated by I3C treatment." (PMID 39722037, 2024). "Another study revealed that IAId significantly reduced skin inflammation in mice with MC903-induced AD-like dermatitis, and this effect was blocked by an AhR antagonist and eliminated in AhR-null mice." (PMID 38250060, 2023). "Recent studies have shown that blocking AhR activation is desirable in some skin conditions; however, in the opposite case, stimulating AhR activation inhibits skin inflammation." (PMID 35625824, 2022). "3-IAId also significantly attenuated skin inflammation in mice with MC903-induced AD-like dermatitis, and this effect was blocked by an AHR antagonist and abolished in AHR-null mice." (PMID 35722100, 2022). "Bacterial peptidoglycan-induced skin inflammation in keratinocytes is regulated by AhR, which modulates the expression of inflammatory genes." (PMID 35625824, 2022). "Both indoles decreased the induction of IL-17 but promoted IL-10 and FoxP3 expression in mice expressing AHR, attenuating skin inflammation." (PMID 34831399, 2021). "While the role of the 5-HT system in skin inflammation has been described, further studies are required to evaluate the relevance of AHR activation in these pathways." (PMID 34831399, 2021). "AHR-CA mice exhibit AD-like phenotypes with frequent scratching, dysfunctional barrier, and increased skin inflammation." (PMID 34437510, 2021). "Tapinarof is a novel AHR-modulating agent that inhibits skin inflammation and enhances skin barrier function." (PMID 34831399, 2021). "Topical application of 3-ICA alleviated skin inflammation in a mouse model of AD-like dermatitis, in part through the inhibition of thymic stromal lymphopoietin expression in keratinocytes in an AhR dependent fashion." (PMID 32635461, 2020). "In a murine dermatitis model, topically applied FICZ activated AHR and significantly reduced the dermatitis score and histological inflammation with a decrease of Il22 gene expression in chronic mite antigen-induced dermatitis." (PMID 31683543, 2019). "Aryl hydrocarbon receptor (AhR) activation suppresses autophagy and promotes skin inflammation through the NF-Kappa B (NF-κB)/p38 mitogen-activated protein kinase (MAPK) signaling pathway, leading to inflammatory cytokine secretion (IL-1β, IL-6, and TNF-α) in keratinocytes." (PMID 40332377, 2025). "In mice, a constitutively active AHR mutant leads to a dermatitis phenotype." (PMID 38344408, 2024).